ANKRA2 (ankyrin repeat family A member 2)
Description:
May regulate the interaction between the 3M complex and the histone deacetylases HDAC4 and HDAC5. May also regulate LRP2/megalin (By similarity).
Synonyms: ANKRA
Tractability: Antibody: UniProt places it where antibodies can reach, with medium confidence; the Human Protein Atlas places it where antibodies can reach. PROTAC: ubiquitination databases record sites on it.
Gene: Protein-coding gene on chromosome 5 (73,552,190 to 73,565,712, reverse strand). Ensembl gene ENSG00000164331.
Subcellular location: Cytoplasm, cytoskeleton; Membrane
Subcellular location (Human Protein Atlas): Plasma membrane; Cell Junctions; Nucleoplasm
Gene Ontology:
Molecular function: histone deacetylase binding; low-density lipoprotein particle receptor binding; protein binding; protein kinase binding; ubiquitin protein ligase binding
Biological process: regulation of protein-containing complex assembly; regulation of gene expression
Cellular component: 3M complex; cytosol; membrane; plasma membrane; protein-containing complex; nucleus; cytoplasm; cytoskeleton
Genetic constraint (gnomAD): Loss-of-function variants: 28 observed, 28.28 expected, observed/expected ratio (o/e) 0.99, 90% interval 0.73 to 1.36. The upper end of that interval is the gene's LOEUF score, 1.36, which puts it in group 5 of 6, group 1 being the genes least tolerant of losing a copy. Missense variants: 263 observed, 321.58 expected, observed/expected ratio (o/e) 0.82, 90% interval 0.74 to 0.91. Synonymous variants: 97 observed, 113.91 expected, observed/expected ratio (o/e) 0.85, 90% interval 0.72 to 1.01.
Homologues: Orthologues: chimpanzee ANKRA2 (99% identical), macaque ANKRA2 (99% identical), dog ANKRA2 (97% identical), rabbit ANKRA2 (97% identical), pig ANKRA2 (97% identical), rat Ankra2l1 (96% identical), guinea pig ANKRA2 (96% identical), mouse Ankra2 (95% identical), rat Ankra2 (93% identical), tropical clawed frog ankra2 (84% identical), zebrafish ankra2 (77% identical). Paralogues in human: RFXANK (44% identical), NFKBIZ (22% identical), NFKBID (21% identical).
Diseases named in the same sentence as ANKRA2 in open-access papers:
ANKRA2 is named in the same sentence as 6 diseases in open-access papers, as found by Europe PMC text mining. Sharing a sentence is not in itself a finding about the gene and the disease. The quoted sentences say what the papers report.
oral squamous cell carcinoma (2 papers, 2015 to 2024). "However, non-synonymous mutations in ANKRA2 have been identified as significantly enriched in oral squamous cell carcinoma, underscoring a potential tumor suppressor role for ANKRA2." (PMID 39181888, 2024).
lung carcinoma (1 paper, 2015).
hematopoietic cancers (1 paper, 2024). "The greater importance of RFX7 in this interaction could explain why only RFX7 mutations, but not ANKRA2 mutations, have been associated with driver events in hematopoietic cancers." (PMID 39181888, 2024).
ANKRA2 also shares sentences with these, for which no sentence is quoted: tumor (4 papers); cancer (1); hearing loss (1).